EGFR (epidermal growth factor receptor)
Diseases named in the same sentence as EGFR in open-access papers (continued):
Sharing a sentence is not in itself a finding about the gene and the disease.
tumor (continued). "Our results on the gene expression profile of size-based enriched circulating tumor cells reveal a dynamic role of EMT and PD-L1 during osimertinib treatment in EGFR-mutant NSCLC patients." (PMID 33504904, 2021). "Meanwhile, we detected the reduction of phospho-EGFR in RHBDF2 knockdown cells, and the phenomenon was also remarkable in the tumor sections of 786-O xenografts." (PMID 34736454, 2021). "Transcriptional reprogramming and selection of tumor cells with an increased FGF-, IGF-, and PDGF- GF-family member gene expression inducing a signaling bypass to the CET EGFR blockade was identified as likely driver of SR in a subset of SR tumors." (PMID 34271981, 2021). "Results from the in vivo experiments confirmed that the downregulation of miR-155-5p enhanced the anti-tumor effect of cetuximab in an MDA-MB-468 xenograft model and on EGFR-overexpressed TNBC cells via inducing cell apoptosis and pyroptosis." (PMID 33472170, 2021). "It has been reported that HE4 can act as a positive regulator in cell adhesion and migration, tumor growth, and cancer metastasis through activating PI3K/AKT and EGFR-MAPK signaling pathways." (PMID 34306124, 2021). "Numerous studies into the molecular events driving GBM highlight the central role played by the Epidermal Growth Factor Receptor (EGFR), as well as the Platelet-derived Growth Factor Receptors PDGFRA and PDGFRB in tumor initiation and progression." (PMID 34830952, 2021). "IGF-1R, EGFR, and VEGF can bind to RTKs, which will activate RAS-RAF-MAPK and PI3K/AKT/mTOR signaling pathways, promoting tumor growth, progression, cell survival, motility, and invasion." (PMID 34638601, 2021). "Eventually, 6-P decreased EGFR expression and inhibited PI3K/AKT signaling to suppress tumor progress." (PMID 34376189, 2021). "There is an extensive autocrine and paracrine crosstalk between EGFR and VEGFR signaling pathways to promote tumor growth and angiogenesis." (PMID 33804477, 2021). "Consequently, we define a novel concept of how the mitogenic and immune modulatory effects of EGFR overexpression may contribute to tumour resistance to immunotherapy, and how EGFR specific inhibitors could be used best to enhance the efficacy of tumour therapy." (PMID 35052732, 2021). "On the other hand, EGFR-L2 was selected from screening a phage display peptide library and also shown to specifically bind to the EGF binding pocked of EGFR, in vitro (using SMMC-7721 cells) and in vivo (using SMMC-7721 tumor-bearing mice)." (PMID 33670650, 2021). "In fact, rechallenge treatment with anti-EGFR drugs has shown promising clinical activity, particularly in patients with plasma RAS and BRAF wild type circulating tumor DNA, as defined by liquid biopsy analysis at baseline treatment." (PMID 33920531, 2021). "Its expression level is found to be correlated with multiple signaling pathways, including EGFR, K-Ras, MAPK, PI3K/Akt, and TGF-β, in various tumor types while facilitating angiogenesis." (PMID 34122424, 2021). "The crosstalk between PRLR and EGFR/HER2 signaling is an additional route that magnifies the actions of their ligands, and further promote tumor growth." (PMID 34572912, 2021). "The rationale to combine dual targeting of EGFR and VEGFR2 derived from the studies which demonstrate that there is significant cross-talk between these two signaling cascades to mediated tumor growth, survival and angiogenesis." (PMID 33804477, 2021). "Therefore, miR-320d may function as a tumor suppressor in EGFR-positive CRC." (PMID 34733314, 2021). "Fluorescently labeled antibody human epidermal growth factor receptor type 2 (HER2)/neu, epidermal growth factor receptor (EGFR) and c-MET have been used to study tumor growth." (PMID 33681162, 2021).
tumor (continued). "SHOC2 inhibitor cooperated with MEK inhibitor or EGFR-TKI impairs cell proliferation and viability in KRAS- or EGFR mutant driven tumor cells." (PMID 34102455, 2021). "Our findings describe a unique pathway of EGFR regulation and identify STAMBP as a potential therapeutic target to suppress LUAD tumor metastasis." (PMID 34102455, 2021). "We chose the second-generation EGFR inhibitor afatinib (BIBW2992), which is known to rescue a lethal EgfrCA-induced tumor phenotype in Drosophila trachea." (PMID 34766923, 2021). "Specific comparison of EGFR, KRAS and BRAF findings were compared following the analysis of tumor tissue, PB cfDNA, MPE cell pellets (cell-blocks) and cell-free MPE samples from the same probands." (PMID 34257581, 2021). "Relative to PLGA-PEG@DOX/anti-EGFR treatment alone, a combination of these PLGA-PEG@DOX/anti-EGFR nano-micelles and UMC was able to inhibit TNBC tumor growth even more effectively at lower concentrations." (PMID 34298600, 2021). "Therefore, anti-EGFR treatment may be considered in right-sided tumours if induction of tumour response for conversion therapy is the primary goal;22 to avoid a negative impact on OS, this approach requires an immediate switch of therapy in patients not responding to induction treatment." (PMID 33154570, 2021). "These EGFR-CAR engineered NK cells demonstrated increased tumor cell lysis capacity, stimulated production of IFN-γ, and further suppressed the tumor growth and subsequently improved survival outcome for a long period." (PMID 35011678, 2021). "For instance, MSC EVs loaded with miR-146 decreased targeted EGFR and NFK-B protein levels in a mouse tumor model along with miR-124 delivery to promote neuroprotection after a brain infarct." (PMID 34527423, 2021). "EGFR-positive non-tumor tissues exhibited significantly lower ERRFI1 expression than EGFR-positive HCC and non-tumor tissues." (PMID 33806040, 2021). "EGFR upregulation occurs in 68% of HCC cases, correlating with tumor aggressiveness, metastasis, and poor prognosis." (PMID 34579396, 2021). "For the validation set of 19 independent tumor samples used for multiplexed IF, we also observed a smaller area of TLS-like lesion in EGFR-MT than EGFR-WT." (PMID 34663810, 2021). "Furthermore, a pilot study testing cetuximab and IPI-926 in patients with recurrent and/or metastatic HNSCC has revealed good tolerability and anti-tumor efficacy, indicating that combinational therapy blocking EGFR and SHH might improve the clinical outcomes for HNSCC patients." (PMID 35048028, 2021). "The finding that co-inhibition of MET and FGFR signalling reduces but does not completely abrogate sphere formation and tumour growth in human cell lines and PDXs may suggest the involvement of other compensatory pathways, such as EGFR, which has been associated with mesenchymal TNBCs88." (PMID 33772015, 2021). "Cetuximab is a monoclonal antibody against the epidermal growth factor receptor (EGFR), and it has been widely investigated since EGFR is overexpressed in CRC and plays important roles in tumor survival." (PMID 34452282, 2021). "The combination of gefitinib, which can down-regulate EGFR/HER3 expression, with sorafenib has been shown to increase tumor inhibition and prevent sorafenib resistance, demonstrating the role of EGFR/HER3 inhibition in the HCC treatment." (PMID 34367979, 2021).
tumor (continued). "Among the down-regulated genes, GLI1 and some other tumor progression related genes were discovered, for example, MMP1, MMP9, NFKB2, TGFA, and EGFR." (PMID 33637972, 2021). "We demonstrated that disrupting this tumor-CAF communication loop by capmatinib and osimertinib combination regimen (suppressing MET/Akt/EGFR) overcame osimertinib resistance." (PMID 33621951, 2021). "ERα-36 has been shown to activate downstream signaling pathways through HB-EGF, SRC, EGFR, HER2, IGF-1R, and ultimately to induce the transcription of growth-promoting genes such as c-Myc and Cyclin D1, and finally to stimulate tumor cell proliferation." (PMID 35096574, 2021). "When disease control is the goal, CT doublet plus anti-EGFR is recommended as the 1L treatment for RAS/BRAF WT left-sided tumor, and CT doublet plus anti-VEGF is recommended for RAS/BRAF WT right-sided tumor." (PMID 34868987, 2021). "The molecular subtype of these two cell lines was compared by detecting HER2, EGFR proteins in PDX-derived organoids and PDX tumor tissues." (PMID 34145270, 2021). "IL10 was observed to activate JAK/STAT3 signaling and induce EGFR expression, which in turn promoted IL10 expression via PI3K/nucleolin signaling to facilitate a feedforward loop that supports tumor development." (PMID 34944848, 2021). "While EGFR was relatively stable in clustered tumor cells, it was gradually activated during the clustering course of PDX tumor cells (indicated by the phosphorylation of EGFR at Y845 and Y1092)." (PMID 33995681, 2021). "The demonstrated cross-reactivity of 806 CAR T cells for EGFR alterations, including amplified wtEGFR, EGFRvIII, and ECD missense mutations, suggests that 806 CAR T cells may be a more efficacious therapeutic strategy to achieve tumor control and prevent tumor escape via target antigen loss." (PMID 34568006, 2021). "In a syngeneic mouse model, JWH-015 decreased lung tumor lesions, tumor growth, and also inhibited macrophage recruitment and EMT to the tumor site via EGFR." (PMID 33916164, 2021). "Overall, first‐generation EGFR TKIs are poorly BBB‐permeable, which greatly limits their efficacy in reducing the CNS tumor burden." (PMID 34374490, 2021). "In surgical specimens, double immunofluorescence has revealed phosphorylated (p-EGFR) and p-VEGFR upregulation in tumor endothelial cells." (PMID 34680445, 2021). "EGFR is a famous receptor found to be overexpressed in most NSCLC cells, and its regulation is essential to manage tumor progression during targeted therapy." (PMID 34576006, 2021). "By activating the epidermal growth factor receptor (EGFR) signaling pathway, it induces tumor cells to develop EMT." (PMID 33517850, 2021). "The nanoparticles exhibited tumor cell targeting, T2-weighted MRI, and MHT of EGFR‐expressing tumors in mice." (PMID 33391494, 2021). "Osimertinib blocked tumour growth in the HCC827 and H3255 xenograft tumours, but failed in A549 xenograft with EGFR WT." (PMID 33247550, 2021). "Gene modified therapy, such as retrovirus transduced epidermal growth factor receptor (EGFR) expressing CD8+ T cell, was validated of having tumor growth suppression efficiency in mice." (PMID 34372912, 2021). "The downregulation of Glut1 and Glut3 protein levels also accounts for the anticancer activity of EGFR TKIs in NSCLC cell lines and xenograft tumor tissues." (PMID 34155348, 2021). "Adherent cells (parental) and tumor spheres (TS) from NSCLC H1975 cells and patient-derived CD133-positive cells were tested for EGFR and Notch1 signaling cascade." (PMID 33922104, 2021).
tumor (continued). "The TAILOR trial compared erlotinib to docetaxel specifically in wt-EGFR tumours and demonstrated significantly poorer ORR, PFS, and overall survival with the anti-EGFR therapy." (PMID 34069119, 2021). "After treatment with erlotinib for 29 days, levels of EGFR and SGLT1 expression were elevated in the xenograft tumor tissues in IHC staining analysis." (PMID 34155348, 2021). "Since FOXM1 is a known regulator of the cell cycle and a downstream molecule of the EGFR/Ras/MAPK signaling pathway, we also analyzed the changes in FOXM1 in the xenograft tumor tissues." (PMID 34830169, 2021). "In the total of 84 HPV-regulated genes, only four genes (EGFR, SNF, UBD, and VCAM1) were differentially expressed when compared with HPV− tumor." (PMID 34646755, 2021). "In human samples, EGFR-positive HCC tissues and their corresponding non-tumor tissues exhibited decreased ERRFI1 mRNA expression." (PMID 33806040, 2021). "The paradoxical increase in tumor migration by GMZ has been described by Xu at al. and is related to the activation of EGFR and STAT3 pathways by this drug." (PMID 34201986, 2021). "It is believed that the RING-type E3 ubiquitin ligase named c-CBL has a role as a tumor suppressor by inducing proteasomal degradation of proteins involved in cell proliferation and migration, such as paxillin, FAK, and EGFR." (PMID 33665742, 2021). "Our study reveals the significant depletion of tumor-infiltrating B cells, CD4+ TFH-like cells, and CD8+ TRM-like cells in EGFR-MT tumors." (PMID 34663810, 2021). "The frequency of each steady-state is modulated by specific genetic modifications (CDK4, PDGFRA, EGFR and NF1); in addition, each single tumor can contain a diversity of states maintained by cellular plasticity." (PMID 34422657, 2021). "This silica coated–CdSe quantum dot is functionalized with antibody, the epidermal growth factor receptor (EGFR), for targeting tumor cells (the probe is named QD–Ab)." (PMID 33525729, 2021). "As we have previously shown, the BATTLE trial data shows TNF and other target genes are tumor promoting in EGFR mutant patients treated with EGFR TKIs, and we confirmed tumor's TNF was elevated by EGFR TKI therapy in vitro, in vivo, and in patients." (PMID 33373873, 2021). "Crosstalk between the oncogenic RTK hepatocyte growth factor receptor (MET), epidermal growth factor receptor (EGFR), and human epidermal growth factor receptor 2 (HER2) are involved in tumor resistance to RTK-targeted therapies." (PMID 32646879, 2021). "These PLGA-PEG/DOX@anti-EGFR nano-micelles were found to significantly improve TNBC treatment outcomes, inhibiting tumor growth while reducing treatment-related toxicity owing to the enhanced EGFR-mediated targeting and UMC-induced vascular permeability." (PMID 34298600, 2021). "However, for patients with a high ΔCT value of EGFR mutations, monotherapy of EGFR-TKIs may not be enough to control the tumor progression." (PMID 34692766, 2021). "The benefit of anti-EGFR treatment for RAS wild-type, left-sided tumours has also been demonstrated in the CALGB 80405 study." (PMID 33154570, 2021). "The most prominent growth factor receptor playing an integral role with GPCRs is the epidermal growth factor receptor (EGFR), regulating tumor growth, invasion, and progression in various human cancers." (PMID 33746610, 2021). "Furthermore, due to tumor heterogeneity, there may be a positive mutation in the EGFR gene that is negative at the tissue biopsy site." (PMID 33314737, 2021). "MiR-133a plays the tumor suppressive role via tageting and regulating the genes like SOX4, EGFR, FSCN1, COL1A1 and so on." (PMID 33391416, 2021). "A promising therapeutic approach is to combine a PD-1/PD-L1 ICI with chemotherapy, EGFR TKI, or other type of ICI with an aim to increase the immunogenicity of tumor cells, or to inhibit immunosuppressive signaling in the TME." (PMID 34113560, 2021).
tumor (continued). "Even though targeting EGFR with tyrosine kinase inhibitor is a good approach against NSCLC, few of them were ineffective regarding tumor response, including Gefitinib." (PMID 34576006, 2021). "In this review, some bioactive iNPs, such as the McAb and EGFR-KTI drug deliveries, are focused on and summarized with emphasis on their applications in tumor therapy, in order to provide new ideas for subsequent research." (PMID 34322025, 2021). "Erlotinib, EGFR inhibitor, in combination with bevacizumab/IFN (BVZ/IFN/ERLO) inhibited tumor growth, promoted blood vessel normalization and reduced lymphatic network in mouse RCC xenografts." (PMID 34209679, 2021). "Furthermore, detection of significantly higher levels of CPAP protein in HNSCC tissues compared to normal tissues, and lack of correlation of CPAP levels with EGFR expression, suggests that tumor associated inflammation contributes to cellular accumulation of potentially non-functional CPAP." (PMID 33889303, 2021). "Knock-down of KDM3A, KLF5, SMAD4 or EGFR in tumour cells influenced the immune TME and re-sensitized tumours to combination immunotherapy." (PMID 33671588, 2021). "Furthermore, tumor heterogeneity could be used to explain why some patients with EGFR‐mutation did not get survival benefit when they received EGFR‐TKIs." (PMID 34704378, 2021). "To investigate the expression correlation between SOCS5 and EGFR, we detected the expression of SOCS5 and EGFR in 62 sets of adjacent normal and tumor tissues by western blot." (PMID 33758600, 2021). "This was confirmed with EGFR FISH analysis of both PDCLs, which showed conservation of EGFR CNVs between patient tumor tissue and matched cell lines." (PMID 34912708, 2021). "In conclusion, we have characterized one novel mechanism of tumor suppressor activity of CSMD1 and we have identified EGFR as the mediator of this action." (PMID 34404439, 2021). "Since EGFR is the hub gene of DEG network, EGFR can possibly affect the prognosis of tumors through the regulation of immune, tumor, and DNA repair pathway." (PMID 34646755, 2021). "Lastly, the effects of AZD3759 and osimertinib on the EGFR and JAK pathways in tumor-bearing mice were confirmed." (PMID 34635007, 2021). "Through inhibition of glucose uptake, EGFR TKI triggered AMPK activation in an LKB1-dependent manner due to the reduction of ATP level to suppress mTOR signaling and tumor growth." (PMID 33335306, 2021). "Using an anti-EGFR/CD3 TDB, hEx3, we visualized and quantified T cell–tumor cell contact and demonstrated a correlation between the degree of cell contact and TDB efficacy." (PMID 32666260, 2021). "The results showed that STAMBP, EGFR, phosphorylated EGFR and ERK were markedly reduced, whereas the ERK levels remained unchanged in the STAMBP knockdown tumor tissues." (PMID 34102455, 2021). "Several evolutionary models, including parallel development and clonal selection have been proposed to explain the discordance rates of EGFR and KRAS between primary tumor and LCBM." (PMID 35201504, 2021). "Thus, EGFR overexpression by IHC shows an association with EGFR amplification but is not of value in predicting the presence of EGFR mutations that implies that IHC negativity in tumours will not exclude the possibility of detecting mutation by gene amplification." (PMID 34367799, 2021). "Its extracellular domain (EpEX) has been shown to activate epidermal growth factor receptor (EGFR) and, through ERK1/2 signaling, promote tumor cell proliferation, migration, and invasion." (PMID 34065396, 2021). "The AG538-loaded EGa1 Nb-liposomes lead to efficient intracellular AG538 delivery, an EGFR blockade, IGF-1R stimulation and the inhibition of tumor cell proliferation." (PMID 34575943, 2021). "Tarloxotinib-E-induced suppression of EGFR, HER2, and HER4 signaling has been shown to impede tumor cell proliferation in vitro, resulting in tumor regression in multiple murine xenograft models." (PMID 34959700, 2021).